CSPG4 (chondroitin sulfate proteoglycan 4)
Diseases named in the same sentence as CSPG4 in open-access papers (continued):
Sharing a sentence is not in itself a finding about the gene and the disease.
cancer (continued). "Moreover, the original murine anti-CSPG4 clone 225.28 has been reported to exhibit direct cancer cell proliferation inhibition properties." (PMID 29375561, 2017). "Expression of CSPG4 seems to correlate with poor prognosis in several cancer types including GBM." (PMID 25537509, 2015). "The inability of hypoxia to overcome the CSPG4 negativity of normal adult ductal cells or 78% of cancer cell lines indicates a lineage-restricted pattern of expression, possibly imposed by hypermethylation, as indicated by our experiments with AZA-treated cell lines." (PMID 24932730, 2014). "To date, CSPG4 has only been targeted in human trials in the form of mouse anti-idiotypic monoclonal antibodies and vaccines that, though safe, proved mostly ineffective for long-term cancer remission." (PMID 25197555, 2014). "Thus, whatever the reason for CSPG4 silencing in normal ductal cells and the majority of cancer cells, hypoxia was incapable to overcome it." (PMID 24932730, 2014). "The lack of prognostic associations, exclusive overexpression of pCSPG4 in benign neoplasm mainly avoiding malignant transformation (SCA), and relatively rare expression of pCSPG4 in carcinoma cell lines argued against the attribution of CSPG4 pro-malignant activity." (PMID 24932730, 2014). "In most cases, only one of the three GAG-attachment sites is substituted by a relatively short chondroitin sulphate chain, whereas in several instances (especially in cancer cells) NG2/CSPG4 seems to be intercalated into the plasma membrane as a GAG-free molecule." (PMID 24386429, 2013). "CSPG4 (Chondroitin Sulfate Proteoglycan 4) or Neuron-Glial Antigen 2 was originally thought to play a role in regulating the blood-brain barrier and tissue homeostasis but recently was found to function in various cell types and to be upregulated in many aggressive cancers as well." (PMID 38533491, 2024). "However, anti-CSPG4 mAbs have shown promise as active anti-cancer reagents." (PMID 36768830, 2023). "Moreover, through GSEA, we found that PD1 blockade cancer immunotherapy directly enriched CSPG4." (PMID 38015710, 2023). "Therefore, CSPG4 is considered a promising target for cancer-targeting immunotherapies." (PMID 37185332, 2023). "Consequently, CSPG4 holds promise as a prognostic marker in the context of cancer." (PMID 38015710, 2023). "Interestingly, in several non-SCC cancer studies, CSPG4 expression has been linked to characteristics associated with reduced malignancy." (PMID 36428658, 2022). "Moreover, CSPG4 expression has been corroborated not only on differentiated cancer cells but also on cancer stem/initiating cells (CIC), considered responsible for recurrences and metastasis, therefore making the CSPG4 an even more interesting target for immunotherapy." (PMID 29534457, 2018). "Therefore, renewed focus on CSPG4 may in future translate into significant benefits for patients with cancer." (PMID 29375561, 2017). "CSPG4, xCT, and TLR2 participate in multiple cancer hallmarks and influence diverse aspects of OSA biology through distinct mechanisms, contributing to OSA pathogenesis and progression." (PMID 41375047, 2025). "Fifteen days following cancer cell grafting the presence of tumors was confirmed by bioluminescence imaging (BLI), and mice were treated with CSPG4 CAR T cells or CD19 CAR T cells, administered as a single dose by tail vein injection." (PMID 40847369, 2025). "In this study, the differentiation of NFs into CAFs via co‐culture with cancer cells was confirmed by quantifying the mRNA expression levels of α‐SMA, FAP, FSP‐1, CSPG4, CXCL12, and HGF using qRT‐PCR." (PMID 39801758, 2025). "Expression validation in the transcriptome, TCGA–BLCA, and GSE13507 datasets confirmed the up-regulation of APOL1, DHX34, and TNK2, and the down-regulation of AHNAK, CSPG4, NCAM1, and PCDHB4 in the cancer group." (PMID 40908816, 2025).
cancer (continued). "Cell surface PGs include syndecans, chondroitin sulfate proteoglycan 4 (CSPG-4), betaglycan, and glypicans, which are expressed in a variety of cancers." (PMID 38946426, 2024). "STAT5A signaling, CSPG4, MMP-1, MMP-3, MMP-8, MMP-9, and LUM are all involved in cancer cell migration, invasion, and metastasis, while PKM supports the growth and survival of cancer cells by favoring aerobic glycolysis." (PMID 39201614, 2024). "The colocalizations of the ofCS with their core proteins (CD44, CSPG4, and SDC1) were detected on various cancer cells by immunofluorescence analysis." (PMID 36746966, 2023). "CSPG4, CD36, CD44 and GD2 were already shown to be involved in cancer cell migration and/or proliferation." (PMID 37803478, 2023). "For example, the ofCS-modified proteoglycan such as ofCS-CD44, -CSPG4, and -SDC1 can present as free form, attached with CTC, or largely with cancer-derived exosomes in plasma." (PMID 36746966, 2023). "To efficiently capture these plasma ofCS glycans, we optimized an ELISA assay with different capture and detection pairs (anti- CD44, -CSPG4, -SDC1, and rVAR2), and tested their performance of detection ofCSPGs in plasma of malignant tumor patients." (PMID 36746966, 2023). "CSPG4 and SDC1 are also essential to cell surface adhesion molecule contributing to cancer progression by promoting cell proliferation, metastasis, invasion, and angiogenesis and is associated with relapse through chemoresistance." (PMID 36746966, 2023). "In cancer cells, NG2/CSPG4 is expressed at the advancing membrane front, specifically at the leading edge of filopodia forming microspikes." (PMID 36428658, 2022). "CSPG4 also seems to enhance malignant cell interactions with the stromal ECM by activating pro-survival signalling cascades, thereby enhancing anti-cancer drug resistance." (PMID 36428658, 2022). "Herein, we attempt to dissect a new perspective on the expression of NG2/CSPG4 in solid organ cancers, such as HCC, pancreatic ductal adenocarcinoma (PDAC), and cancers of the lungs or kidneys, and its clinical significance as a novel immunotherapeutic target." (PMID 35891187, 2022). "It has been demonstrated that chondroitin sulfate proteoglycan 4 (CSPG4), a scaffold protein composed of chondroitin sulfate and proteoglycan with multiple cancer-promoting functions, is overexpressed in TNBC." (PMID 35280756, 2022). "Immunotoxins were coupled with specific cell-targeting proteins that can bind to CSPG4, to CD133-expressing cancer stem cells, to EGFR, or to VEGFR." (PMID 31936595, 2020). "We also examine other potential candidate components of the plasma membrane (proteoglycan chondroitin sulfate proteoglycan 4, or CSPG4) and cellular machinery of motility (UNC-45A) in relation to cancer cell TNTs." (PMID 30333973, 2018). "Chondroitin sulfate proteoglycan 4 expression was described in TNBC primary lesions and metastatic tumor cells from pleural infusions, including cancer stem cells." (PMID 29375561, 2017). "The mAb9.2.27 is one of the first monoclonals ever to be produced against NG2/CSPG4, as well as one of the antibodies having the longest track-record of being exploited to target NG2/CSPG4-positive cancer cells in vitro and in vivo." (PMID 24127551, 2013). "CSPG4 CAR T cells demonstrated strong antitumor activity against all the tested cell lines, by achieving near complete eradication of target cells at high ratios (cancer cell lysis of 72.2 ± 15.6% at the 1:1 E: T and 50.3 ± 20.7% at the 1:2 E: T)." (PMID 40847369, 2025). "Direct, Fab-mediated growth inhibition also occurred in most CSPG4-expressing cancer cells in the absence of effector cells." (PMID 39409881, 2024). "They observed that CSPG4-specific antibodies isolated from vaccinated rabbits triggered ADCC of cancer cells in the presence of human PBMCs but not complement-dependent cytotoxicity (CDC) in the presence of human serum." (PMID 39409881, 2024).
cancer (continued). "Accordingly, a relative increase of certain markers can be detected in the profile of cancer cell-derived EVs compared with normal primary astrocyte-EVs: CD44 and CD90 were elevated in LN18-EVs; CD36, CD54, CSPG4, and GD2 in LN229-EVs; CD13, CD49e, CD49f, and CD90 in NCH82-EVs." (PMID 37803478, 2023). "Functional studies are now warranted to address the functional role of CSPG4 expression in GIST, and notably, whether it is dependent on the link with the immune response we observed, and/or with direct influence on cancer cells." (PMID 35267618, 2022). "This suggested that cancer cells from these tumors showed no signs of resistance to the toxic effects of anti-CSPG4-(PDD)." (PMID 32331483, 2020). "The expression of the CSPG4 antigen in other malignancies suggests 212Pb-225.28 would also be worthy of evaluation for targeted α-particle RIT of additional types of cancer in future studies." (PMID 29561763, 2018). "Through a FAK-independent mechanism, CSPG4 could increase the activation of ERK 1 and 2 and sustaining cancer cell migration also through this pathway." (PMID 28668095, 2017). "Treatment of CSPG4+ cancer cells selectively and effectively inhibit thymidine incorporation with negligible effect on CSPG4-negative cell lines." (PMID 28657611, 2017). "Current advances in cancer vaccines and vaccine adjuvants have not been applied to CSPG4." (PMID 39409881, 2024). "Moreover, these identified biomarkers in cancer-specific CSPG4-positive EV subtypes can be directly applied in non-invasive liquid biopsy to monitor cancer progression or response to therapy." (PMID 37823055, 2023). "In contrast, antibodies directed toward TACAs present on CSPG4 may have greater cancer specificity, thereby providing additional protection for normal tissues." (PMID 36768830, 2023). "Even though anti-id antibody strategies or mimotope vaccines are currently not in the spotlight, these early studies indicate that CSPG4 may be a promising target for vaccine-based cancer immunotherapy." (PMID 29375561, 2017). "IPMNs, which may have distinct pathways to cancer progression, show an intriguing CSPG4 distinction between non-malignant and malignant entities; only the latter tend to up-regulate both pancreatic and circulating CSPG4 levels." (PMID 24932730, 2014). "Thus, the artificial down-regulation of CSPG4 in pCSPG4-expressing cancer cells should not impede their malignant behavior." (PMID 24932730, 2014). "However, CSPG4 is not reported to have any intrinsic catalytic functions but rather serves as a scaffold protein, promoting cancer growth and progression through involvement in pathways regulating epithelial-to-mesenchymal transition (EMT), cell motility, and proliferation." (PMID 39409881, 2024). "Overexpression of CSPG4 has not been reported to be a result of genetic aberrations such as gene amplifications or chromosome translocation, suggesting CSPG4 may not be a primary driver in the onset of cancer." (PMID 29375561, 2017).
colorectal (3 papers, 2021 to 2023). "Using a spinal cord injury (SCI) mouse model, we describe that some infiltrated bone marrow-derived macrophages (BMDMΦ) are early contributors to NG2/CSPG4 expression and secretion after SCI." (PMID 33815067, 2021).
heart disease (2 papers, 2022 to 2025). "For example, in regard to vascular mural progenitor cells, NG2/CSPG4 is expressed on heart cardiomyocytes in large vessels, specifically smooth muscle cells (SMAs), and on PCs in the microvasculature, making it even more meaningful for heart disease than it has been in studies on the CNS." (PMID 35891187, 2022). "By addressing these interconnected pathological features, CSPG4.CAR-T emerges as a promising strategy for restoring cardiac integrity in mdx mice and, potentially, in patients with dystrophic heart disease." (PMID 40724839, 2025).
infection (2 papers, 2021 to 2023). The state of being infected such as from the introduction of a foreign agent such as serum, vaccine, antigenic substance or organism. "Two C. difficile exotoxins (TcdA and TcdB) are major virulence factors associated with these infections, and chondroitin sulfate proteoglycan 4 (CSPG4) is a potential receptor for TcdB, but its pathophysiological relevance and the molecular details that govern recognition remain unknown." (PMID 34145250, 2021). "Clostridioides difficile TcdB exploits CSPG4 as a receptor for binding to and entering target cells during infection." (PMID 36972308, 2023). "There was bloody fluid accumulation in tissues dissected from WT mice after infection, whereas there was much less fluid accumulation in tissues from CSPG4 KO mice." (PMID 34145250, 2021). "In addition, infection led to 100% moribundity of WT mice by 48 h, whereas only 50% of CSPG4 KO mice reached moribundity." (PMID 34145250, 2021). "Indeed, previous work has shown that CSPG4-/- mice are resistant to C. difficile disease, further supporting the notion that reducing levels of this receptor during infection could benefit the host." (PMID 36972308, 2023).
infectious disease (1 paper, 2023). A disorder directly resulting from the presence and activity of a microbial, viral, or parasitic agent in humans. "Our work not only has identified a critical pathway for regulating CSPG4 but may have also discovered a new approach for combating infectious disease and possibly reducing the use of antibiotics." (PMID 36972308, 2023).
CSPG4 also shares sentences with these, for which no sentence is quoted: neuroblastoma (6 papers); squamous cell carcinoma (6); hepatocellular carcinoma (5); hematologic cancers (3); acute lymphoblastic leukemia (2); prostate carcinoma (2); uveal melanoma (2); adenocarcinoma (1); B-cell lymphoma (1); Cerebral ischemia (1); cyclopia (1); Duchenne muscular dystrophy (1); dysplastic nevi (1); epidermolysis bullosa (1); fibrosarcoma (1); fibrosis (1); follicular thyroid carcinoma (1); genetic disorders (1); hereditary spastic paraplegia (1); Hydrocephalus (1); ischemia (1); lymph node metastases (1); mastocytoma (1); mental illness (1); mucinous adenocarcinoma (1); myocardial infarction (1); neurofibromatosis type 1 (1); neurological diseases (1); osteoarthrosis (1); pancreatic ductal adenocarcinoma (1).
A further 5 diseases each share a sentence with CSPG4 in 1 paper.